IL6 (interleukin 6)
Diseases named in the same sentence as IL6 in open-access papers (continued):
Sharing a sentence is not in itself a finding about the gene and the disease.
tauopathy (9 papers, 2016 to 2026). Neurodegenerative disorders involving deposition of abnormal tau protein isoforms (tau proteins) in neurons and glial cells in the brain. "A recent study using a rodent model of tauopathy reported that pathogenic forms of tau can enter brain endothelial cells and induce vascular dysfunction, associated with an increase of neuroinflammatory markers, including IL-6 and MCP1, which have been reported to increase BBB permeability." (PMID 41495815, 2026). "Significantly, it has been found that immune activation contributes to the speeding progression of tauopathies through inflammatory cytokines such as interleukin-6 (IL-6)." (PMID 40808925, 2025). "By contrast, in neurodegenerative conditions such as AD and tauopathy, microglial cell expression of the IL-6-response cluster genes were unchanged or only slightly increased." (PMID 35429976, 2022). "Neuroinflammation can amplify itself by increasing tauopathy and Aβ deposition through inflammatory cytokines such as IL-1β, IL-6, and TNF-α." (PMID 36389075, 2022). "Further, neuroinflammation can amplify itself by increasing tauopathy and Aβ deposition through microglia-secreted pro-inflammatory cytokines such as IL-6 and TNF-α." (PMID 33059746, 2020). "It was found that tauopathy reduced basal NE levels in forebrain areas, while the gene expression of IL-6 was increased in all selected areas at the same time." (PMID 26792515, 2016). "Tauopathy significantly affected basal levels of NE as well as gene expression of IL-6, one of the major pro-inflammatory cytokines in the brain." (PMID 26792515, 2016). "In addition, the LC exhibited exaggerated expression of pro- and anti-inflammatory mediators (IL-6, TNFα, inducible nitric oxide synthases 2 (iNOS2), and interleukin 10 (IL-10)) in transgenic rats suggesting that tauopathy affects also the immune background in LC." (PMID 26792515, 2016). "Concordantly, CST reduced expression of CD68, GFAP, IL-6, TNF-α, CXCL1, and CXCL10, extending its known peripheral anti-inflammatory actions 20,38 to the central nervous system and establishing CST as a regulator of neuroimmune homeostasis in Tauopathy." (PMID 41509358, 2026).
thalassemia (9 papers, 2013 to 2024). An inherited blood disorder characterized by a decreased synthesis of one of the polypeptide chains that form hemoglobin. "However, high levels of inflammatory markers such as interleukin-6 and soluble vascular adhesion molecules have been linked to impaired endothelial function in patients with thalassemia." (PMID 26346439, 2015). "Analysis of cytokines showed a wide variability of the IL-6 and IL-10 values both in the group of total thalassemia patients (THAL) and in healthy subjects (CTR), with extremely high values of IL-6 in some patients." (PMID 36699704, 2022). "In thalassemia patients η1and η1/η200 correlated positively with the cytokines IL-6 and IL-10 (p < 0.001), and negatively with the adhesion molecule L-selectin (η1, p < 0.05; η1/η200, p < 0.05)." (PMID 36699704, 2022). "As thalassaemia MPs could induce TF, IL-6, IL-8, ICAM-1, VCAM-1 and E-selectin expression, the potential functional consequences of MPs influence on the adhesion of endothelial cells and monocytes was examined." (PMID 30158562, 2018). "As the study groups were patients with major thalassemia and it plays a role in the pathophysiology of thalassemia inflammation, it leads to an increase in TNF and IL6." (PMID 24575288, 2013). "On the other hand, in thalassemia patients also observed aspect a reduction in leptin partly due to the genetic defect This possibility is suggested that TNF and IL6 affect leptin much more than pituitary- hypothalamus axis." (PMID 24575288, 2013). "Notably, the magnitude of LPS-mediated IL-6 induction was more pronounced in the presence of iron dextran treatment, while such response was not affected by thalassemia." (PMID 33987030, 2021).
uveal melanoma (9 papers, 2017 to 2024). A melanoma derived from melanocytes of the uveal tract. "Uveal melanoma cells and tumor-associated macrophages have also been shown to produce IL-6." (PMID 34283046, 2021). "With the exception of constitutive tyrosine phosphorylation, which remained unaffected in the investigated uveal melanoma cells, chelidonine influenced both IL-6 induced activation and constitutive serine phosphorylation of STAT3 in a similar fashion." (PMID 34884773, 2021). "Recently, IL-6 has also been shown to induce EMP by direct STAT3 binding to the JunB promoter in uveal melanoma cells." (PMID 34361105, 2021). "Among factors that enhance cancer growth and spreading, both IL-6 and IL-8 play a fundamental role not only in cutaneous but also in uveal melanoma." (PMID 33182777, 2020). "Interestingly, abnormally elevated levels of many cytokines, including IL-2, IL-4, IL-6 and IL-8, have been observed in the vitreous of eyes from patients with uveal melanoma." (PMID 35163491, 2022). "Therefore, we studied the potential effects of this alkaloid on serine and IL-6-induced tyrosine phosphorylation of STAT3 in human uveal melanoma cells using flow cytometry and confocal microscopy." (PMID 34884773, 2021). "Similarly, IL-6 treatment increased migration in uveal melanoma cells, together with reduced expression of cell adhesion molecules (TJP1, TJP2 and CDH1), and increased levels of focal adhesion molecules (FN1 and ICAM-1) and fibronectin receptor integrin subunits." (PMID 34361105, 2021). "Mutation of this −280 STAT DRE totally abolished responsiveness of the HTR2B basal promoter toward IL-4 and IL-6, therefore establishing that transcription of the HTR2B gene is under the regulatory influence of STAT proteins in uveal melanoma." (PMID 35163491, 2022). "Interleukin-6, a major activator of STAT3, is present in elevated concentrations in uveal melanomas, suggesting contribution of dysregulated STAT3 activation to their pathogenesis." (PMID 34884773, 2021). "Here we show that chelidonine, the major alkaloid component of Chelidonium majus L., exerts opposing effects on IL-6-induced activation and constitutive serine phosphorylation of STAT3 in human uveal melanoma cells." (PMID 34884773, 2021). "According to our results, chelidonine increased the efficiency of constitutive serine phosphorylation, whereas it abrogated IL-6-induced tyrosine phosphorylation and nuclear translocation of STAT3 in the investigated human uveal melanoma cells." (PMID 34884773, 2021). "In addition, IL-6, Mig, and IP-10 levels were higher in uveal melanoma than in ARMD, probably due to the stronger inflammatory state in uveal melanoma." (PMID 27878431, 2017).
aortic stenosis (8 papers, 2011 to 2026). Aortic valve stenosis is a aortic valve disease caused by the incomplete opening of the aortic valve. "Stratifying by aortic valve morphology, PALMD rs6702619 and IL6 rs1800795 polymorphisms were associated with aortic stenosis in tricuspid aortic valve (TAV) patients only." (PMID 36337884, 2022). "From the literature we know that pro-inflammatory markers such as Tumor necrosis factor-alpha (TNF-alpha), receptor activator of nuclear factor-kappa B (NF-κB) ligand (RANKL) and Interleukin-6 (IL-6) are associated with aortic stenosis." (PMID 27488119, 2017). "For example, the IL6R locus strengthens the link between inflammation and aortic stenosis beyond the previously identified IL6 locus." (PMID 41419685, 2026). "Among the previously replicated loci for aortic stenosis is interleukin-6 (IL6; β = 0.051, P = 9.2 × 10−45)." (PMID 41419685, 2026). "In this regard, our group has previously demonstrated, both in vivo and in vitro, that statin administration reduces EAT secretion of IL-6 and IL-8 levels in patients with aortic stenosis." (PMID 35187125, 2022). "Based on the microarray data, we chose three genes known to be mechanosensitive and associated with aortic stenosis: MMP-1, MMP-3, and IL-6." (PMID 21876831, 2011). "Notably, elevated levels of citrullinated histone H3 have been positively correlated with both interleukin-6 levels and the severity of aortic stenosis, as assessed by aortic valve area." (PMID 40076529, 2025). "Even comparing BV/TV levels for homozygotes of the risk allele (GG genotype for PALMD and CC genotype for IL6) with the levels of other genotypes, after adjustment by diagnosis of aortic stenosis, the differences were not statistically significant." (PMID 36337884, 2022).
Barrett esophagus (8 papers, 2017 to 2025). Esophageal lesion lined with columnar metaplastic epithelium which is flat or villiform. "STAT3 regulates IL-6 genes and expression of STAT3 increases during the transition from Barrett’s metaplasia to adenocarcinoma." (PMID 28757556, 2017).
bile duct cancer (8 papers, 2012 to 2026). "We investigated the relationship between plasma levels of Interleukin (IL)-6 and the risk of developing advanced fibrosis and bile duct cancer from chronic Opisthorchis infection." (PMID 22629477, 2012). "Only two studies focused on the correlation between clinical characteristics in patients with bile duct cancer and IL-6, and both included few patients." (PMID 30038723, 2018). "Serum IL-6 correlated with bile duct cancer tumor mass, which they used to define tumor burden, indicating that IL-6 has potential as a prognostic biomarker and could be useful in assessing the efficiency of treatment." (PMID 30038723, 2018). "The use of IL-6 as a prognostic biomarker seems promising for patients with gastric-, pancreatic-, and mayble also for bile duct cancer." (PMID 30038723, 2018). "It is reported that the concentration of IL-6 is significantly higher than normal levels in the patients with bile duct carcinoma (BDC), speculating that IL6 has the diagnostic significance of BDC." (PMID 30671125, 2018). "Finally, we show that a single plasma IL-6 measurement has excellent positive predictive value for the detection of both advanced bile duct fibrosis and bile duct cancer in regions with high O. viverrini transmission." (PMID 22629477, 2012). "Importantly, elevated serum IL-6 is also observed in patients treated with PDT and has been correlated with a better prognostic in patients (with primary bile duct cancer) submitted to treatment with hematoporphyrin-PDT." (PMID 31906092, 2019).
Bovine mastitis (8 papers, 2020 to 2025). INFLAMMATION of the UDDER in cows. "It is well-studied that proinflammatory cytokines, such as TNF-α and IL-6, play a central role in the inflammatory response associated with bovine mastitis." (PMID 40577324, 2025). "The development of bovine mastitis is closely associated with the overexpression of pro-inflammatory cytokines, particularly IL-1β, IL-6, and TNF-α, which play pivotal roles in inflammatory cascades." (PMID 40901059, 2025). "Notably, stimulation of whole blood from cattle with TLR 2 and 4 ligands or heat-killed bacteria known to cause bovine mastitis, resulted in increased IL-6 levels compared to unstimulated controls." (PMID 40533814, 2025). "In a recent study, our group validated the inhibitory effect of glyceryl 1,3 distearate in suppressing the IL1β, IL6, IL8, and CXCL3 overexpression induced by LPS from Escherichia coli, a bacterium causing bovine mastitis." (PMID 39193343, 2024). "Pro-inflammatory cytokines, such as IL-1β, and IL-6, play a key role in inflammatory diseases including bovine mastitis, and IL-1β and IL-6 are well-studied to be involved in up-regulation of inflammatory responses." (PMID 33251265, 2020). "Pathological conditions cause altered expression levels of pro-inflammatory cytokines, such as TNF-α, which is produced early in the inflammatory response, IL-1β, which is crucial for both adaptive and innate immunity, and IL-6, which is thought to be one of the main biomarkers of bovine mastitis." (PMID 40005856, 2025).
chronic endometritis (8 papers, 2016 to 2025). A non-granulomatous or granulomatous chronic inflammation of the endometrium. "A significant increase in plasma IL-6 concentration was reported in mares with chronic endometritis and subacute suppurative endometritis." (PMID 41226467, 2025). "Previous studies revealed that inflammatory factors IL-6 and TNF-α were significantly increased in the menstrual blood of women with chronic endometritis." (PMID 37446399, 2023). "Nonetheless, in another study, IL-6, IL-1β and TNF-α levels were investigated in menstrual effluents of women with chronic endometritis." (PMID 27152525, 2016). "Elevated concentrations of total IgM, IgA, and IgG have been observed in chronic endometritis (CE) and recurrent implantation failure (RIF), as well as significantly elevated cytokine levels, including interleukin-6 (IL-6) and pro-IL-1β, which have also been observed in these clinical conditions." (PMID 39684937, 2024). "For this aim, expression of mRNAs for Toll-like Receptor 2 and 4 (TLR 2/4), interleukin 1β (IL-1β), interleukin 6 (IL-6) and tumor necrosis factor α (TNF) was examined in control mares versus either mares suffering from chronic endometritis (ChE) or subacute suppurative endometritis (SSE)." (PMID 27152525, 2016). "Furthermore, a logistic regression analysis provided evidence that the IL-6/TNF-α-based model, excluding IL-1β, is a significant predictor of chronic endometritis, which is in accordance with the present results." (PMID 27152525, 2016).
colorectal adenocarcinoma (8 papers, 2019 to 2025). The most common type of colorectal carcinoma. "CT26 colorectal adenocarcinoma bearing mice are commonly used to induce cancer cachexia with several accompanying symptoms including hepatic functional impairments, adipose and skeletal muscle wasting, and an increase in IL-6 concentration." (PMID 31717643, 2019). "The increased secretion of pro-inflammatory cytokines such as, IL-1β, IL-6, and TNF-a in macrophages (THP-1 cell lines) or IL-6, IL-8, and TNF-a in human colorectal adenocarcinoma cells (Caco-2 cells) was observed following exposure to 59 nm or 100 μm PS." (PMID 39120391, 2024). "In another study, the proinflammatory markers CD68, CD15, IL-6, and TLR4 were upregulated in colorectal adenocarcinoma compared to normal mucosa or premalignant conditions." (PMID 36649244, 2023). "Furthermore, in several cell culture models of intestinal dysfunction, established with human colorectal adenocarcinoma cells, PAs from various sources could decrease the level of inflammatory mediators (e.g., TNF-α, IL-6 and IL-8) and had a protective effect on the cell layer integrity." (PMID 35052987, 2022).
dilatation (8 papers, 2011 to 2025). "Progressive aortic dilatation was observed when both fibrillin-1 and IL-6 were deficient." (PMID 30883599, 2019). "Using the ROC curve analysis, we evaluated the predictive power of the serum CRP levels, WBC count, ANC, PLR, and degree of cervical dilatation in maintaining pregnancy for >4 weeks after rescue cerclage compared to the IL-6 concentration in the amniotic fluid." (PMID 38552048, 2024). "In addition, a positive relationship was found between the severity of diabetic glomerular lesions (mesangial dilatation) and IL-6 mRNA levels in glomerular mesangial cells and podocytes, indicating that IL-6 may positively influence the dynamics of the ECM accumulation in the kidney." (PMID 36045667, 2022). "This study demonstrated that the degree of cervical dilatation at diagnosis; WBC count, ANC, and CRP levels in the maternal peripheral blood; and IL-6 concentration in the amniotic fluid significantly differed between the successful and failure groups (all P < .05)." (PMID 38552048, 2024). "Inhibition of IL6 signaling is a promising strategy for treating AAA, but not other types of aneurysmal disease." (PMID 39633572, 2025).
diverticulitis (8 papers, 2014 to 2025). An infection that develops in the diverticula of the intestinal tract. "In susceptible RA patients, the neutralization of IL-6 may contribute to diverticulitis, potentially altering colonic contractions and leading to an unusual inflammatory presentation." (PMID 40066438, 2025). "Also, previous studies on circulating IL-6 showed a correlation between chronic systemic inflammation and the risk of diverticulitis." (PMID 37627532, 2023). "Lastly, we found a significant increase in IL-6 levels during the study nights during which the patients had diverticulitis, and this increase was correlated to changes in NREM sleep (including N2 sleep), REM sleep, and fatigue scores." (PMID 26290799, 2015). "Given our results, it is intriguing to consider local administration of IL-6 in the intestine after injury, such as diverticulitis, to promote healing." (PMID 25478789, 2014). "We performed a retrospective analysis of surgical bowel resection cases that were performed to excise areas of intestinal perforations that occurred due to a variety of etiologies (i.e. diverticulitis and trauma) to test if IL-6 expression was induced in areas of injury." (PMID 25478789, 2014).
enthesitis (8 papers, 2019 to 2025). Inflammation at the site of insertion of ligaments, tendons, and other fibrous structures into bone. "Other key genes involved in enthesitis were up‐regulated including CSF2 (encoding granulocyte–macrophage CSF), IL12B, IL6, and notably CD80 and CD83 encoding the M1‐associated costimulatory receptors." (PMID 40320905, 2025). "The demographic, clinical, and biological variables measured were age, time since PsA diagnosis, smoking, type of treatment used, clinical form, presence of enthesitis, dactylitis (present or past), fatigue, tumor necrosis factor (TNF)-alpha, and interleukin 6 (IL-6)." (PMID 38978782, 2024). "The production of pro-inflammatory factors, including IL-6 and PGE2, by mechanosensitive cells may participate in the enthesitis process." (PMID 33046134, 2020). "However, therapeutic targeting of IL-6 with clazakizumab demonstrated limited efficacy in improving enthesitis, dactylitis, or joint inflammation, with no clear dose-response relationship, leading to discontinuation of clinical trials." (PMID 41583484, 2025).
Ewing sarcoma (8 papers, 2015 to 2025). A small round cell tumor that lacks morphologic, immunohistochemical, and electron microscopic evidence of neuroectodermal differentiation. "In studies on Ewing Sarcoma, the activation of CD99 in macrophages was shown to induce the secretion of characteristic chemokines such as IL1β, IL6, TNFα, and markers CD80 and CD86 by M1 macrophages." (PMID 41000385, 2025). "Knockdown of ETS1 or inhibition of ETS1 with a pan ETS inhibitor TK216 (currently in phase I clinical trial (NCT026570095) for Ewing sarcoma), downregulated AXL, IL6, and EFEMP1, suggesting ETS1 transcriptionally activates these genes." (PMID 38762181, 2024). "Since, miR-22 was reported to target and regulate KDM3A in Ewing sarcoma, these findings suggest that miR-22 may regulate both PHF8 and KDM3A in LNCaP cells, at steady state as well as in the presence of CS-FBS or IL-6." (PMID 27689328, 2016). "Consequently, the origin of IL6 in serum of patients with Ewing sarcoma might not be attributed to the ES cells themselves in all instances." (PMID 26215971, 2015).
fibrosarcoma (8 papers, 2017 to 2025). A malignant mesenchymal fibroblastic neoplasm affecting the soft tissue and bone. "They observed that in murine CD163-deficient macrophages the expression of IL6 was decreased, while the silencing of IL6 expression in wildtype macrophages was sufficient to negate the macrophage-induced proliferation of murine fibrosarcoma cells." (PMID 35327375, 2022). "In fibrosarcoma-derived cells, IL-6 signaling depends on the presence of Jak1." (PMID 28708884, 2017). "CD163-KO TAMs had decreased production of IL-6 and CXCL2 in comparison to WT TAMs in co-culture with MCA205 (mouse fibrosarcoma) cells." (PMID 36686729, 2022). "Another group has reported that PAI-1 promotes M2 polarization of monocytes via an IL6/STAT3 autocrine loop in fibrosarcoma; however, we did not observe M2 polarization following rhPAI-1 treatment." (PMID 33311557, 2021).